LGALS3 (galectin 3)
Diseases named in the same sentence as LGALS3 in open-access papers (continued):
Sharing a sentence is not in itself a finding about the gene and the disease.
psoriasis (20 papers, 2012 to 2025). An autoimmune condition characterized by red, well-delineated plaques with silvery scales that are usually on the extensor surfaces and scalp. "Galectin-3 deficient in epidermal keratinocytes resulted in a spontaneous development of psoriasis-like phenotype." (PMID 35075118, 2022). "Based on the increased Vmax and robust thermal stability of IDOC4S4, we fused it to the anchoring moiety galectin 3, to evaluate its effectiveness in a mouse model of psoriasis." (PMID 41059158, 2025). "To date, galectin-3 is the most extensively investigated member in the context of psoriasis, for which elevated serum levels have been consistently reported, including our own research." (PMID 41226378, 2025). "Galectin-3 (gal-3) regulates many different biological processes and diseases, which are common accompanying diseases of psoriasis." (PMID 35053087, 2022). "The mean of serum galectin-3 concentration in patients with psoriasis was 6.23 ± 0.487 ng/mL before treatment and after 5.74 ± 0.461 ng/mL, and was significantly higher compared to the control group: 3.44 ng/mL ± 0.537 ng/mL (p < 0.01)." (PMID 35053087, 2022). "The data cited, as well as our own results and the FDA approval of gal-3 as a cardiovascular biomarker, confirm that galectin-3 is a significant multifunctional biomarker of psoriasis and its comorbidities, especially myocardial." (PMID 35053087, 2022). "The mean serum galectin-3 level in patients with psoriasis was significantly higher compared to the control group (p < 0.01)." (PMID 35053087, 2022). "We demonstrated that serum galectin-3 concentration was significantly increased in patients with psoriasis comparing to the healthy persons." (PMID 35053087, 2022). "Galectin-3, which belongs to the galectin family of β-galactoside-binding lectins, is a psoriasis-specific protein downregulated in psoriatic epidermis." (PMID 35075118, 2022). "Galectin-3 (gal-3) is a multifunctional regulator of various biological processes and diseases, which are common comorbidities in psoriasis." (PMID 35053087, 2022). "Galectin-3 expression in dermal capillaries has a role in the reorganization of the capillary system and the involvement of inflammatory cells in psoriasis." (PMID 33150039, 2020). "The role of galectin-3 in wound healing and various inflammatory skin diseases, such as atopic dermatitis and psoriasis, has been characterized previously." (PMID 33150039, 2020). "Our previous work revealed that galectin-3 can influence the course of psoriasis and cardiometabolic comorbidities; moreover, galectins-1, 2 and 12 may be involved in metabolic complications associated with psoriasis." (PMID 41226378, 2025). "Administration of recombinant Galectin-3 ameliorated IMQ-induced psoriasis-like dermatitis." (PMID 35075118, 2022). "Importantly, particularly in terms of participation in the pathogenesis of psoriasis, upregulation of galectin-3 is involved in differentiation and maturation of keratinocytes." (PMID 35053087, 2022). "The results are not very optimistic, but the study group was very little with no control group, and further randomized controlled clinical trials and dose-finding research are definitely needed in order to define the galectin-3 inhibitors’ actual and potential use for treating psoriasis." (PMID 35053087, 2022). "However, the exact role of the downregulation of fibroblast galectin-3 in the development of psoriasis remains undefined." (PMID 32731552, 2020). "Serum galectin-3 level did not correlate with psoriasis severity expressed with PASI score (p > 0.05)." (PMID 35053087, 2022).
systemic sclerosis (20 papers, 2013 to 2025). A chronic disorder, possibly autoimmune, marked by excessive production of collagen which results in hardening and thickening of body tissues. "In conclusion, combining N-terminal prohormone brain natriuretic peptide, periostin, and galectin-3 as serum biomarkers enhances risk stratification and sensitivity in detection of cardiac disease in patients with systemic sclerosis." (PMID 40743121, 2025). "Galectin-3 was also demonstrated to be an independent predictor of all-cause and cardiovascular death in patients with systemic sclerosis." (PMID 35141299, 2021). "Galectin-3 (Gal-3) has been proposed to have a pathogenic role in systemic sclerosis (SSc)." (PMID 37652913, 2023). "In addition, LGALS3 genetic variation encoding Gal-3 have been associated with systemic sclerosis patients and cognitive functions at old age." (PMID 36232314, 2022). "The aim of this study was to investigate the serum concentration of metabolic adipose tissue factors: adiponectin, resistin, leptin and endothelial proteins: endothelin-1, fractalkine and galectin-3 in patients with systemic sclerosis." (PMID 31667578, 2020). "We compared year-long changes in endothelin-1 (ET-1), galectin-3 (Gal-3), renal indices (eGFR, ACR), and quantitative CT densitometry in COPD and systemic sclerosis-associated ILD (SSc-ILD)." (PMID 41010963, 2025). "Galectin-3 expression is higher in SLE and systemic sclerosis patients with active diseases than those with an inactive one." (PMID 28593065, 2017). "The serum levels of galectin-3 were elevated in patients with RA, JIA, Behçet’s disease, or systemic sclerosis." (PMID 24416634, 2013). "Except for galectin-3, the role of these compounds in systemic sclerosis has not been assessed either comprehensively across the entire disease spectrum or specifically concerning the subtype of the disease." (PMID 40362179, 2025). "However, except for galectin-3, and to a lesser degree suPAR, the utility of these molecules has not yet been extensively tested in systemic sclerosis." (PMID 40362179, 2025). "In line with its in vitro pro-inflammatory function, it has been shown that the levels of galectin-3 are elevated in the serum or nidi of patients with inflammatory diseases including RA, systemic lupus erythematosus (SLE), Behçet’s disease, and systemic sclerosis." (PMID 24416634, 2013). "However, galectin-3 expression is not directly correlated with the disease activity and severity indexes in each SLE and systemic sclerosis patient, nor with the duration of the disease." (PMID 28593065, 2017).
acute coronary syndrome (19 papers, 2015 to 2026). Signs and symptoms related to acute ischemia of the myocardium secondary to coronary artery disease. "Background/Objectives: We investigated the potential diagnostic role of galectin-3 (Gal-3) in patients presenting with suspected acute coronary syndromes (ACS)." (PMID 39124770, 2024). "In patients with acute coronary syndrome, higher plasma levels of galectin-3 levels were found to be associated with poor survival rate." (PMID 34677196, 2021). "So far, data about a relation between galectin-3 plasma levels in the patients with acute coronary syndromes and preexisting AF and LVEF, left ventricular end-diastolic and end-systolic volume indices and left atrial volume index, were not published." (PMID 29118378, 2017). "In addition, serum galectin-3 levels increase in the early phase following acute coronary syndrome since it is involved not only in the development but also in the destabilization of atheromatous plaques." (PMID 38519721, 2024). "There is no published data on the prognostic significance of galectin-3 plasma levels in the patients hospitalized for acute coronary syndromes with preexisting AF." (PMID 29118378, 2017).
chronic obstructive pulmonary disease (19 papers, 2013 to 2025). A chronic and progressive lung disorder characterized by the loss of elasticity of the bronchial tree and the air sacs, destruction of the air sacs wall, thickening of the bronchial wall, and mucous accumulation in the bronchial tree. "A previous study also reported that CSE induced the release of galectin-3 in airway epithelial cells, which was higher in chronic obstructive pulmonary disease-derived cells compared with control-derived cells." (PMID 31737173, 2019). "Exogenous galectin-3 can enhance efferocytosis of apoptotic cells by monocyte-derived macrophages (MDMs) as well as by AMs in patients with chronic obstructive pulmonary disease (COPD) which highlights the potential of galectin-3 in the regulation of macrophage function in NEA." (PMID 30606211, 2019). "In the pathogenesis of chronic obstructive pulmonary disease (COPD), TRIM16 and galectin-3 play a synergistic role in initiating lysosomal membrane permeabilization (LMP) and inducing lysosomal autophagy (a selective lysosomal autophagy process), mediating lysosomal damage." (PMID 36249749, 2022). "Furthermore, the levels of circulating galectin-3 were higher in smokers compared to nonsmokers with acute exacerbation of chronic obstructive pulmonary disease." (PMID 36272642, 2022). "Galectin-3 has previously been shown to improve the ability of airway macrophages to ingest apoptotic cells (efferocytosis) in chronic obstructive pulmonary disease (COPD) and may be of interest in non-eosinophilic asthma (NEA) which is also characterised by impaired efferocytosis." (PMID 30606211, 2019).
lung adenocarcinoma (19 papers, 2016 to 2025). A carcinoma that arises from the lung and is characterized by the presence of malignant glandular epithelial cells. "For example, a combination of TTF-1 (lung and thyroid), galectin-3 (100% in papillary thyroid cancers), and napsin A (lung adenocarcinomas) is used to determine the tumour origin of a lung mass in patients with thyroid nodules." (PMID 33706755, 2021). "The data indicate that Galectin-3 and TLR4 expression are abnormally up-regulated in lung adenocarcinoma tissues; Galectin-3 affects lung adenocarcinoma cell proliferation and migration through activating TLR4/NF-κB pathway and NEAT1 expression." (PMID 29788922, 2018). "In their case, overexpression of the Thomsen-Friedenreich antigen (Galß1-3GalNAc) by lung adenocarcinoma metastatic cells allowed them to interact with galectin-3 expressed on pro-tumorigenic leucocytes." (PMID 26908442, 2016). "Similarly, we found that galectin-3 expression was notably elevated in both the TME of lung adenocarcinoma patients and in the supernatant of LLC." (PMID 39135069, 2024). "Consequently, in this study, we investigated the prognostic impact of galectin-1 overexpression as well as galectin-3 overexpression on the patients with lung adenocarcinoma after definitive radiation therapy." (PMID 35280768, 2022). "Association between galectin-3 (Gal-3) expression level, and clinical outcome of T1 lung adenocarcinoma has not been clarified." (PMID 32630393, 2020). "Here, we explored the upstream regulatory factors and mechanisms of NEAT1 abnormal overexpression in lung adenocarcinoma, and further suggest a regulatory path formed by Galectin-3, TLR4, NF-κB and NEAT1 that may contribute to the hyperproliferation and migration of lung adenocarcinoma cells." (PMID 29788922, 2018). "Indeed, Galectin-3 is suggested as an immunotherapeutic target improving the outcome of inhibitory checkpoint inhibition in cancer immunotherapy, were Galectin-3 inhibition for example was demonstrated to augment the PD-L1 response in a mouse model of lung adenocarcinoma." (PMID 39759523, 2024). "In further preclinical studies, a structurally similar galectin-3 inhibitor, GB1107, inhibited lung adenocarcinoma growth and metastasis, and augmented the tumor response to programmed death-ligand 1 blockade." (PMID 36914828, 2023). "For instance, in a lung adenocarcinoma tumor sphere-model, which mimic an immunosuppressive TME, galectin-3 is released in the TME and modulated the tumor infiltrating immune cells such as regulatory T cells (Treg)." (PMID 38259448, 2023). "Oral administration of a galectin-3 inhibitor (GB1107) reduced human and mouse lung adenocarcinoma growth and blocked metastasis in a syngeneic model." (PMID 34572756, 2021). "The data indicate that Galectin-3 induces TLR4/NF-κB signaling activation, followed by NEAT1 expression upregulation, and ultimately promotes lung adenocarcinoma cell proliferation and migration." (PMID 29788922, 2018). "Galectin-3 and TLR4 expression are abnormally up-regulated in lung adenocarcinoma tissues, and positively correlated with NEAT1 expression." (PMID 29788922, 2018). "The overexpression of tumor galectin-1, but not galectin-3, is associated with poor LRPFS of patients with lung adenocarcinoma after thoracic radiation therapy." (PMID 35280768, 2022). "Moreover, the mRNA expression and protein levels of Galectin-3 and TLR4 in lung adenocarcinoma samples were much higher than those in normal lung tissues." (PMID 29788922, 2018). "Galectin-3 reportedly serves as a ligand of TLR4 and promotes TLR4, MyD88 and p-p65 expression; we investigated whether Galectin-3 could modulate lung adenocarcinoma cell proliferation and migration through TLR4/NF-κB/NEAT1." (PMID 29788922, 2018). "Inhibiting Galectin-3-induced TLR4 signaling activation, thus to reduce p65-activated NEAT1 expression might be a promising strategy of suppressing lung adenocarcinoma cell proliferation and migration." (PMID 29788922, 2018).
lung adenocarcinoma (continued). "Herein, we also observed that Galectin-3 overexpression remarkably induced TLR4 protein expression, as well as lung adenocarcinoma cell proliferation and migration; next, we further investigated whether Galectin-3 exerts its function through downstream NF-κB and NEAT1." (PMID 29788922, 2018). "We confirmed that Galectin-3 as a ligand of TLR4 induced TLR4 signaling activation in lung adenocarcinoma cells, thereby activating downstream p65 nucleus translocation, promoting NEAT1 expression, and finally affecting lung adenocarcinoma cell proliferation and migration." (PMID 29788922, 2018). "Galectin-3 and TLR4 were both overexpressed in lung adenocarcinoma tissues, compared to those in non-tumor control." (PMID 29788922, 2018). "As a further confirmation of these data, the mRNA expression of Galectin-3 and TLR4 in lung adenocarcinoma and non-cancerous tissue samples were examined." (PMID 29788922, 2018).
Parkinson disease (19 papers, 2017 to 2025). A progressive degenerative disorder of the central nervous system characterized by loss of dopamine producing neurons in the substantia nigra and the presence of Lewy bodies in the substantia nigra and locus coeruleus. "One variant of the Gal-3 gene (LGALS3) is associated with Parkinson’s disease risk at p = 9 × 10–15 and 4 × 10–16." (PMID 32581723, 2020). "Recently, we found galectin-3 (gal3) to be a central regulator of microglial immune response in Parkinson’s disease and in prolonging sustained microglial activation in AD." (PMID 36740709, 2023). "Furthermore, serum galectin-3 is increased in Parkinson’s disease patients and correlates to the Hoehn-Yahr stage." (PMID 37491623, 2023). "In neurodegenerative conditions such as Alzheimer’s disease (AD), Parkinson’s disease (PD), and amyotrophic lateral sclerosis (ALS), Lgals3 has been established as a biomarker in serum, plasma, and/or cerebrospinal fluid (CSF)." (PMID 38728287, 2024).
paroxysmal AF (19 papers, 2015 to 2026). "Galectin-3 levels were significantly elevated solely in the paroxysmal AF group, reflecting ongoing atrial fibrosis." (PMID 40709024, 2025). "Individuals with paroxysmal AF exhibited elevated galectin-3 and hsTnI concentrations compared to both new-onset AF patients and controls, indicating more advanced fibrosis and myocardial stress." (PMID 40709024, 2025). "Serum galectin-3 levels were also significantly higher in patients with persistent AF than in those with paroxysmal AF." (PMID 28785588, 2017). "The study demonstrated that serum galectin-3 levels had an independent correlation with the extension of LA fibrosis demonstrated by DE-MRI in paroxysmal AF patients." (PMID 28785588, 2017). "In addition to recurrence, galectin-3 was also found to be associated with the progression of AF: in a longitudinal study of patients with paroxysmal AF, patients with progression into persistent AF had significantly higher baseline Gal-3 than patients who remained paroxysmal." (PMID 41590667, 2026). "To summarize, galectin-3, MMP-9, GDF-15, and PIIINP are promising markers in the prediction of paroxysmal AF, while TGF-β1 shows a lower potential." (PMID 28785588, 2017). "Galectin-3 plasma level was not significantly different between patients with paroxysmal AF and those with permanent/persistent AF." (PMID 29118378, 2017).
Cerebral ischemia (18 papers, 2010 to 2025). Restriction of arterial blood supply to the brain associated with insufficient oxygenation to support the metabolic requirements of the tissue. "Accumulated evidence has indicated that galectin-3 appeared to function as a significant regulator participating in the neuroinflammatory reaction caused by cerebral ischemia and reperfusion." (PMID 33953667, 2021). "The brain-related pathways demonstrated that PKall, KNG, B2KR, IL-6, TNF-α, IL-1β, LGALS-3, and PAR 2 were linked to superoxide anion generation and brain ischemia." (PMID 34867349, 2021). "In contrast, targeted deletion of Galectin-3 exacerbated ischemic brain injury and neurodegeneration after cerebral ischemia suggesting a neuroprotective role of Gelectin-3 after brain damage." (PMID 31156388, 2019). "Furthermore, one study found that the targeted deletion of galectin-3 could aggravate ischemic damage after cerebral ischemia." (PMID 33686023, 2021). "Interestingly, higher acute-stage plasma galectin-3 levels were associated with subsequent development of delayed cerebral ischemia and cerebral infarction, but not cerebral vasospasm." (PMID 29414883, 2018). "Galectin-3 appears to be one of the crucial initiators of microglia activation and proliferation following ischemic brain injury, but role of activation of microglial cells upon brain ischemia remains questionable, whether it could be advantageous or injurious." (PMID 32455781, 2020). "Galectin-3/MAC-2, a member of a class of carbohydrate-binding proteins, has been known to play a role in tissue repair following cerebral ischemia and mediates microglial phagocytosis." (PMID 21187959, 2010).